ITGAL (integrin subunit alpha L)
Diseases named in the same sentence as ITGAL in open-access papers (continued):
Sharing a sentence is not in itself a finding about the gene and the disease.
thyroid (1 paper, 2023). "Our findings of lower ITGAL mRNA expression in cases with lymphovascular invasion (p = 0.0427) and extrathyroidal extension (p = 0.0111) and high mRNA expression in cases with lymphocytic infiltrate (p = 0.0244), reinforce a tumor suppressive role for LFA-1 in thyroid tumorigenesis." (PMID 36906717, 2023).
viral myocarditis (1 paper, 2022). Myocarditis that is caused by an infection with a viral agent. "The proteins ICAM1 (M3WBF1_FELCA) and CDH17 (M3WMR7_FELCA) were upregulated, while ITGAL (M3 WC52_FELCA) and ITGAE (M3W8N0_FELCA) were downregulated in the viral myocarditis pathway." (PMID 36290246, 2022).
tumor (79 papers, 1997 to 2026). "RCC cancers overexpress ITGAL compared to normal control tissue and greater expression is associated with higher tumor grade." (PMID 40766148, 2025). "We found that LFA-1 (encoded by ITGAL) exhibited the highest expression among all α integrins in tumor-infiltrating Tregs." (PMID 38787791, 2024). "The integrin α-L chain encoded by the ITGAL gene is involved in regulating immune cell activity in the tumor microenvironment." (PMID 38646528, 2024). "The observation made in our analysis indicates that there is a consistent association between higher levels of ITGAL expression and decreased tumor purity across all the tumor types that were examined." (PMID 39605903, 2024). "In NSCLC tumor tissues, ITGAL was downregulated compared with matched paracancerous tissues, and low ITGAL expression was associated with a poor prognosis of NSCLC patients." (PMID 38646528, 2024). "Consulting the literature revealed that elevated expression of these cytokines positively associated with ITGAL expression were all involved in the promotion of tumor cell survival, stemness, and proliferation." (PMID 35999614, 2022). "In adenocarcinoma patients, ITGAL was associated with N stage of tumor.The effects of resveratrol on ITGAL were less reported." (PMID 34633989, 2021). "In this study, our data from RNA-Seq analysis showed that ITGAL gene encoding CD11a integrin is upregulated in tumor-infiltrating PMN-MDSCs, compared with I-MDSCs." (PMID 31941522, 2020). "Functional enrichment analysis revealed a correlation between ITGAL and immune cell infiltration, while single‐cell data indicated predominant expression of ITGAL in NK cells, which was significantly associated with tumour immune invasion and response to immunotherapy." (PMID 38613346, 2024). "Furthermore, the stemness score, which is associated with drug resistance and continuous tumor cell proliferation, was also evaluated in relation to ITGAL expression." (PMID 39605903, 2024). "ITGAL expression linked to tumor prognosis across 27 cancers." (PMID 39605903, 2024). "Additionally, ITGAL displays noteworthy associations with infiltration of immune cell and immune checkpoint related genes, indicating its potential as a promising target in tumor immunotherapy." (PMID 39605903, 2024). "In addition, the expression of ITGAL was correlated negatively with the tumour mutation burden." (PMID 38613346, 2024). "Therefore, more investigation was necessary to determine whether ITGAL expression is associated with tumor outcome." (PMID 35399517, 2022). "As a member of the Integrin family, ITGAL plays a significant role in tumor chemotaxis and immune responses." (PMID 40838069, 2025). "Tumor volume and weight were slightly reduced by CM treatment, which was enhanced by KMT2D overexpression, and the anti-cancer effect was abolished by ITGAL deficiency." (PMID 40718439, 2025). "In SELPLG-deficient tumor-infiltrating T cells, expression analysis of the same selected genes revealed that CCR7 and ITGAL were significantly upregulated in SELPLG-negative cells that infiltrated the tumor model." (PMID 41394860, 2025). "There was a significant correlation between the expression of ITGAL and the tumor microenvironment in a number of cancers." (PMID 38646528, 2024). "Recent studies have discovered that ITGAL is enriched in the tumor microenvironment, drawing much interest in oncology." (PMID 38646528, 2024). "The second finding was that ITGAL expression was significantly higher in the tumor tissues of female patients than in the tumor tissues of male patients, suggesting that the tumor immune microenvironment differs between females and males." (PMID 38646528, 2024). "The role of ITGAL and its ligands in the tumor microenvironment has been considered as a potential therapeutic target." (PMID 38646528, 2024).
tumor (continued). "According to the EstimateScore, the analysis suggests that the expression of ITGAL is correlated with increased levels of immune infiltration in several tumor types, including KIPAN, SKCM-M, SKCM, PAAD, SKCM-P, and UVM." (PMID 39605903, 2024). "In order to determine the suitability of immune checkpoint therapy, the correlation between ITGAL expression and TMB (Tumor Mutational Burden) as well as MSI (Microsatellite Instability) was investigated and compared across various cancer types." (PMID 39605903, 2024). "Existing studies have shown that ITGAL can affect the prognosis and survival of tumors such as melanoma and gastric cancer through tumor immunity." (PMID 39605903, 2024). "Considering the contribution of TME to tumor onset and progression and its prognostic effect, HNSCC (GSE103322 and GSE139324) were analyzed in TISCH to assess the expression of ITGAL in TME-linked cells." (PMID 39605903, 2024). "The potential of ITGAL as a biomarker is substantiated by its differential expression levels across distinct pathological stages within the same tumor." (PMID 39605903, 2024). "We collected 20 patients from our institution for immunohistochemical verification of ITGAL expression in normal and tumour tissues, and the results showed that the expression of ITGAL was significantly higher in normal tissues." (PMID 38613346, 2024). "To further elucidate the immune properties of ITGAL related to the tumor immune microenvironment, we evaluated genes involved in immune stimulation and found that 30 genes were positively associated with ITGAL in LUAD and LUSC." (PMID 38646528, 2024). "To decipher the molecular features of ITGAL‐expressing cells that were distinct from those of the other cells in tumour samples, we obtained the different marker genes by using the FindAllMarkers." (PMID 38613346, 2024). "Subsequently, immunohistochemistry results for tissue microarray showed that ITGAL expression was mainly elevated in tumor stroma and areas with highly infiltrated immune cells." (PMID 38646528, 2024). "The findings from our research present a potential strategy to target ITGAL for anti-tumor purposes, with a specific focus on modulating the immune microenvironment of the tumor." (PMID 39605903, 2024). "The correlation between ITGAL expression and clinical factors, as well as the immunophenotypes of tumor-infiltrating immune cells, were also analyzed." (PMID 38646528, 2024). "With the help of mIF, we examined the expression of ITGAL in tissue microarrays and the distribution of tumor-infiltrating immune cells." (PMID 38646528, 2024). "Despite numerical variations in the three scores, there was a consistent overall trend indicating that ITGAL plays a significant regulatory role in the tumor microenvironment to some extent in malignant conditions." (PMID 39605903, 2024). "A significant difference was observed between tumor and paraneoplastic lung samples for ITGAL mRNA expression in TCGA-LUAD and TCGA-LUSC(P<0.001)." (PMID 38646528, 2024). "By analyzing the IHC results of each patient, we found that paraneoplastic tissues had significantly higher ITGAL expression compared to matched tumor tissues." (PMID 38646528, 2024). "At the same time, we hope to propose a targeted anti-tumor strategy for ITGAL by regulating the tumor immune microenvironment (TME) and find corresponding anti-cancer drugs." (PMID 39605903, 2024). "At the same time, we collected tumour tissue from 128 patients for immunohistochemistry, and the results showed that patients with high expression of ITGAL had better OS and DSS." (PMID 38613346, 2024). "In a subsequent study, we examined the expression of ITGAL mRNA in tumor and peritumor lung tissue samples from five patients with NSCLC." (PMID 38646528, 2024). "Amanda’s study showed that ITGAL promotes Cx3cr1 expression, cx3cl1-mediated migration and Ccl5 expression in microglia, thereby promoting microglial infiltration and tumor formation." (PMID 39605903, 2024).
tumor (continued). "In order to further validate our findings, we examined ITGAL expression at various stages of NSCLC tumor progression and lymph node metastases using the TCGA database." (PMID 38646528, 2024). "ITGAL is remarkably associated with CD8+T cells and crucial in the tumor immune microenvironment of pan-cancer." (PMID 39605903, 2024). "The expression of ITGAL was higher in tumor tissues from female patients than male patients, and in tumor tissues from early-stage patients than advanced-stage patients." (PMID 38646528, 2024). "We found that ITGAL was enriched in the mesenchyme in NSCLC tumor tissues, while ITGAL-expressing regions in tumor tissues were accompanied by immune cell aggregation and high expression of immune cell markers." (PMID 38646528, 2024). "Studies have been conducted to explore ways to inhibit the invasion and metastasis of tumor cells by interfering with ITGAL-ICAM interactions." (PMID 38646528, 2024). "A review of the literature indicates that elevated expression of these cytokines, which are positively correlated with ITGAL expression, is all involved in promoting tumor cell survival, stemness, and proliferation." (PMID 37388230, 2023). "We further explore the relationship between ITGAL levels and the tumor immune microenvironment of NSCLC." (PMID 37256932, 2023). "Studies confirmed that ITGAL plays crucial roles in cancer progression and tumor immune microenvironment." (PMID 37256932, 2023). "Tumor necrosis promotes metastasis and is associated with poor prognosis; the presence of ITGAL, ITGAX, and TMEM119 in tumor necrosis suggests their roles in facilitating NSCLC progression." (PMID 37835514, 2023). "We found that ITGAL was aberrantly expressed in different tumor tissues through databases, including GEPIA, Timer, TCGA, and TNMplotter." (PMID 37388230, 2023). "PRDX6, MAGOHB, NUCKS1, DCAF13, and TXN displayed opposite trends on their potential facilitation of CTL function as well as correlations with immune checkpoints and TILs (tumor-infiltrating lymphocytes) compared to ITGAL, ITGAX, and TMEM119 in NSCLC." (PMID 37835514, 2023). "By applying RNA-seq data from various cancer types in the TCGA, we investigated the differential expression of ITGAL between tumor and surrounding healthy tissues." (PMID 35399517, 2022). "A pan-cancer analysis indicated that ITGAL was differentially expressed between normal and tumor tissues in 24 out of 33 tumor types, with AML showing the most prominent difference." (PMID 35999614, 2022). "In conjunction with these results, ITGAL played a vital function in recruiting and modulating TILs in GC, and it is worth to continue investigating the molecular mechanism and function of ITGAL in modulating tumor microenvironment." (PMID 35399517, 2022). "Next, in order to get a well grasp of the significance and possible molecular mechanism of ITGAL expression in tumor development, we observed the correlation between the ITGAL expression and clinical–pathological features of GC in the KM plotter." (PMID 35399517, 2022). "Correlation analysis between ITGAL and related genes and markers of immune cells in Tumor Immune Estimation Resource (TIMER2.0)." (PMID 35399517, 2022). "A study of cancer stages revealed that ITGAL in the middle and late-stage cancers was significantly higher expressed than in the early stages, suggesting a potential function for ITGAL in tumor development and migration." (PMID 35399517, 2022). "TIMER, GEPIA, and TISIDB databases were used to comprehensively investigate the correlation between ITGAL and tumor infiltration immune cells." (PMID 35399517, 2022). "Among these, 4 genes (CD8A, CD3E, CCL4 and ITGAL) were reported to have close relationship with tumor immune microenvironment and to be involved in various pathological processes of EC35–37." (PMID 34131259, 2021).
tumor (continued). "It has been shown that in some tumor cell lines delivery of control plasmid DNA caused significant increase in the expression of following ISGs: IRF7, STAT1, MIG, MICA and ITGAL." (PMID 26839680, 2016). "Additionally, ITGAL showed downregulation in tumours, suggesting a reduction in Th17 cell differentiation activity, which, in turn, impairs anti-tumour immunity." (PMID 40429821, 2025). "For one thing, high expression of ITGAL inhibits the malignant progression of tumour cells; for another, ITGAL plays a crucial role in recruiting and modulating NK cells in LUAD, which could promote the secretion of cytokines in NK cells." (PMID 38613346, 2024). "Moreover, subcluster analysis of the NK cells revealed that the expression levels of ITGAL was higher in normal tissues than in tumours." (PMID 38613346, 2024). "Functional enrichment analyses showed that ITGAL was significantly correlated with cell immune response and immune checkpoint, consistent with the analysis of single‐cell sequencing in paired samples of normal and tumour." (PMID 38613346, 2024). "Our findings suggested that ITGAL is critically involved in tumor immunity." (PMID 39605903, 2024). "The expression levels of SELL and ITGAL in circulating sEVs of NB patients may indicate the activation or suppression status of T cells or other immune cells in tumor tissues." (PMID 39228987, 2024). "It was highlighted by these findings that ITGAL is crucially involved in tumor immunity." (PMID 39605903, 2024). "ITGAL expression was higher in paracancerous tissues than tumor tissues." (PMID 38646528, 2024). "Moreover, the correlation linking ITGAL to immunomodulatory genes, including MHC, chemokines, and genes related to chemokine receptors, provides additional evidence of its association with tumor immunity." (PMID 39605903, 2024). "In addition, the expression of ITGAL in different patients (tumour vs. normal; PCR/MPR vs. SD/PD) can be effectively distinguished through immunohistochemistry." (PMID 38613346, 2024). "Moreover, ITGAL was prominently highly expressed in the stroma area of the tumor tissues and on the membrane and cytoplasm of macrophages and lymphocytes aggregated in these areas." (PMID 38646528, 2024). "On the other hand, TECs also might contribute to lymphocyte migration into the tumor via ICAM1/ICAM2-(ITGAL + ITGB2) interactions with T/NK cells." (PMID 39093451, 2024). "Furthermore, we confirmed that ITGAL expression affect the tumour microenvironment (TME) through regulation of the expression of cytokines in NK cells of LUAD." (PMID 38613346, 2024). "In order to verification the different expression of ITGAL in tumor and peritumoral tissues." (PMID 39605903, 2024). "We aim to uncover the critical role ITGAL plays in NSCLC, the possible connection between ITGAL and tumor-infiltrating immune cells, and the mechanism by which ITGAL may affect this process." (PMID 38646528, 2024). "In T-cell immunotherapy, ITGAL proteins may be involved in tumor recognition by immune cells as the starting point for cytotoxic T cells to generate immune synapses with cancer cells." (PMID 38646528, 2024). "Considering the complexity of the tumor immune microenvironment, animal models may provide a better understanding of ITGAL’s role in NSCLC immunity." (PMID 38646528, 2024). "Our findings may provide a targeted anti-tumor strategy for ITGAL by influencing the tumor immune microenvironment to treat HNSCC." (PMID 39605903, 2024). "Data were obtained from The Cancer Genome Atlas (TCGA), Gene Expression Omnibus (GEO), and Clinical Proteomic Tumor Analysis Consortium (CPTAC) databases to explore the relationship between ITGAL expression and prognosis, as well as the immune cell infiltration in patients with NSCLC." (PMID 38646528, 2024). "Furthermore, among patients undergoing immunotherapy, those with a favourable treatment response (PCR/MPR) exhibited higher ITGAL infiltration in tumour tissues compared to those with the SD/PD." (PMID 38613346, 2024).